ARL17A (ARF like GTPase 17A)
Description:
Putative small GTP-binding protein cycling between an inactive GDP-bound and an active GTP-bound form.
Synonyms: ARF1P2; ARL17P1
Tractability: Antibody: its Gene Ontology location is reachable by antibodies, with medium confidence. PROTAC: ubiquitination databases record sites on it.
Gene: Protein-coding gene on chromosome 17 (46,499,780 to 46,579,695, reverse strand). Ensembl gene ENSG00000185829.
Subcellular location (Human Protein Atlas): Nucleoplasm
Gene Ontology:
Molecular function: GTP binding; GTPase activity
Biological process: intracellular protein transport
Cellular component: nucleoplasm; plasma membrane
Homologues: Orthologues: dog ARL17A (44% identical), mouse Arf2 (44% identical), rat Arf1 (44% identical), Caenorhabditis elegans arf-1 (42% identical), Drosophila melanogaster Arf1 (42% identical), zebrafish arf2a (42% identical). Paralogues in human: ARL17B (100% identical), ARF1 (42% identical), ARF3 (42% identical), ARF4 (34% identical), ARF5 (34% identical), ARF6 (31% identical), ARL1 (29% identical), TRIM23 (28% identical), ARL4A (25% identical), ARL3 (24% identical), ARL4C (24% identical), ARL5B (23% identical), and 18 more.
Diseases named in the same sentence as ARL17A in open-access papers:
ARL17A is named in the same sentence as 18 diseases in open-access papers, as found by Europe PMC text mining. Sharing a sentence is not in itself a finding about the gene and the disease. The quoted sentences say what the papers report.
schizophrenia (2 papers, 2024 to 2026). A major psychotic disorder characterized by abnormalities in the perception or expression of reality. "Representative associations were observed for SPPL2C, MAPT, LRRC37A2, and ARL17A, whose expression in the brain was significantly associated with schizophrenia as well as with MD and λ1 of the right inferior cerebellar peduncle (ICP)." (PMID 41522603, 2026). "In particular, the expression of SPPL2C, MAPT, LRRC37A2, and ARL17A was significantly associated with schizophrenia as well as with MD and λ1 of the right ICP." (PMID 41522603, 2026). "Many genes that were found in this analysis, including CRHR1, ARL17A, NSF, and OGFOD2, have been implicated in previous GWAS of regional brain volumes, and have also been linked to brain disorders, including epilepsy, schizophrenia, and brain cancer." (PMID 39269986, 2024).
chondrosarcoma (1 paper, 2014). A malignant cartilaginous matrix-producing mesenchymal neoplasm arising from the bone and soft tissue. "Two mutations in ARL17A have detected in chondrosarcoma cells." (PMID 25496518, 2014).
medulloblastoma (1 paper, 2022). A malignant, invasive embryonal neoplasm arising from the cerebellum. "For the last selected circular fusion in medulloblastoma, the ARL17B--KANSL1, it should be noted that the coding sequences of ARL17A (NM_001113738.2) and ARL17B (NM_001039083.5), including the exon 3 at the fusion, are identical." (PMID 35804907, 2022).
melanoma (1 paper, 2023). A malignant, usually aggressive tumor composed of atypical, neoplastic melanocytes. "Associations with the presence of TERT promoter mutations revealed an overlap of 30 genes in the three bulk RNA-seq cohorts (in melanoma and across entities), of which six genes were consistently up- or down-regulated (up: ARL17A, FBF1, KAZALD1, PRAF2; down: PLEKHB2, RASGRP3)." (PMID 37418389, 2023).
progressive supranuclear palsy (1 paper, 2021). A rare late-onset neurodegenerative disease characterized by supranuclear gaze palsy, postural instability, progressive rigidity, and mild dementia. "However, rs113986870 also significantly influenced the expression of another gene in this region, ARL17A, that was previously linked to progressive supranuclear palsy by analysis of gene expression and methylation." (PMID 33907181, 2021).
cancer (3 papers, 2021 to 2022). A tumor composed of atypical neoplastic, often pleomorphic cells that invade other tissues. "Out of them, we selected 4 communities associated with genes CASP8, MAN2C1, BTN3A2 and ARL17A which are all reported in literature as possibly involved in cancer." (PMID 35061909, 2022).
ARL17A also shares sentences with these, for which no sentence is quoted: Alzheimer disease (2 papers); COVID-19 (2); tumor (2); brain cancer (1); brain disorder (1); cognitive decline (1); epilepsy (1); glioblastoma (1); lung carcinoma (1); lymphoma (1); neurodegenerative disease (1); prostate carcinoma (1).